FANCD2 (FA complementation group D2)
Diseases named in the same sentence as FANCD2 in open-access papers (continued):
Sharing a sentence is not in itself a finding about the gene and the disease.
ovarian carcinoma (32 papers, 2005 to 2025). A malignant neoplasm originating from the surface ovarian epithelium. "In contrast, a study conducted on 181 ovarian cancer patients provided evidence of an increased survival rate in patients with the FANCD2 mutation." (PMID 39051418, 2024). "Our data also indicated that FANCD2 mutations, especially the FANCD2 span mutation, were related to family history and early onset of ovarian cancer." (PMID 38509102, 2024). "We have also shown that patients with high expression of FANCD2 have a higher risk of early recurrence of ovarian cancer." (PMID 32165999, 2020). "Low expression of FANCD2 has been linked to development of ovarian cancer and enhanced sensitivity to therapy." (PMID 36046263, 2020). "In this study, we show that cytoplasmic localization of FANCD2 is associated with positive prognosis in ovarian cancer patients." (PMID 32165999, 2020). "In addition, the association between Fancd2 and drug resistance has been reported in multiple myeloma, ovarian cancer, non-small cell lung cancer, and head and neck cancer in vitro." (PMID 38218826, 2024). "Also, studies carried out on ovarian carcinoma samples verified that the risk of recurrence and death are highly associated with the expression level of FANCD2." (PMID 39051418, 2024). "Many ovarian cancer patients (OCPs) have reduced FANCD2 expression, whereas overexpression of the protein is associated with a poor prognosis, especially in patients undergoing taxane-platinum therapies." (PMID 41405958, 2025). "Recently, there are studies that up-regulation of Fancd2 expression is positively correlated with tumor size and poor prognosis in ovarian cancer, nasopharyngeal carcinoma, glioblastoma, and EC." (PMID 38218826, 2024). "For instance, nuclear and cytoplasmic localization of FANCD2 was identified in ovarian carcinoma from both healthy and ovarian carcinoma sufferers." (PMID 35509981, 2022). "It has also been reported that double knockdown of POLQ and FANCD2 decreased the tumor volumes of xenotransplants of a human ovarian cancer cell line." (PMID 34206946, 2021). "In another study, the upregulation of Polθ and its positive correlation with expression of many DNA repair genes including TOPBP1, BLM, RAD54L, FANCI, BRCA1, FANCD2, ATAD5 was reported in HR-deficient epithelial ovarian cancer cells." (PMID 34762643, 2021). "We also examined the nuclear and cytoplasmic expression of FANCD2 in vitro using ovarian surface epithelial cells (OSEs) derived from normal patients (n = 3) or ovarian cancer patients (n = 5)." (PMID 32165999, 2020). "Expression of the Fanconi Anemia complementation group D2 protein (FANCD2) is reduced in ovarian surface epithelial cells (OSE) in patients with ovarian cancer." (PMID 32165999, 2020). "In this study, we examined the nuclear and cytoplasmic distribution of FANCD2 in ovarian cancer tissue microarray." (PMID 32165999, 2020). "These seemingly paradoxical observations suggest that more research is needed to delineate the role of FANCD2 in modulating ovarian cancer biology." (PMID 32165999, 2020). "Using a TMA with 181 patient ovarian cancer tissue samples we examined the nuclear and cytoplasmic expression of FANCD2 protein." (PMID 32165999, 2020). "Mono-ubiquitination of FANCD2, which is required for its DNA repair function, was exclusively present in the nuclear fraction in OSEs from both normal patients and patients with ovarian cancer." (PMID 32165999, 2020).
ovarian carcinoma (continued). "Reduced expression of FANCD2 has been reported in sporadic and hereditary breast cancer and in OSE cells from women with high risk of developing ovarian cancers." (PMID 32165999, 2020). "In fact, epigenetic silencing of FANCF via promoter methylation and reduced levels of FANCD2 have been previously detected in ovarian cancer." (PMID 22253870, 2012). "Interestingly, we were able to produce knockout cell lines using the PEO1 ovarian cancer cell line, for another FA pathway protein, FANCD2 using the same methodology." (PMID 38711848, 2024). "We applied fit Chi-square calculation to evaluate the mutation with ovarian cancer risk and found the mutation of FANCD2 that significantly fails to conform Hardy–Weinberg equilibrium (P-value 2.76e − 06)." (PMID 38509102, 2024). "Finally, we found that germline deleterious mutations in FANCD2 and RECQL4 were likely susceptibility genes for ovarian cancer, and we should be more cautious to these two genes." (PMID 38509102, 2024). "The Fancd2 knock-out (KO) animal model has formerly been shown to develop epithelial ovarian cancer, with the purported precursor lesion hypothesised to develop from primordial ovarian follicles prematurely devoid of their germ cell." (PMID 37174061, 2023). "To evaluate the clinical relevance of the study, we applied Kaplan-Meier survival analysis and found that patients with breast or ovarian cancer with high expression of FANCD2 and XRCC4 had poorer overall survival than those with low expression of FANCD2 and XRCC4." (PMID 35642638, 2022). "Then, we focused on genes traditionally associated with breast/ovarian cancer or other malignancies, and identified 23 missenses, 2 splicing, and 2 UTR variants mainly affecting genes involved in DNA repair, such as RAD51, RAD54B, PMS1, FANCD2, XRCC1, and BLM." (PMID 35893033, 2022). "In total our work suggests that FANCD2 may play a role in preventing oncogenic transformation of the OSEs but elevated expression of FANCD2 in ovarian cancer may be predictive of platinum resistance." (PMID 32165999, 2020). "We sought to determine whether subcellular localization of FANCD2 correlates with patient outcome in ovarian cancer." (PMID 32165999, 2020). "Interestingly overexpression of FANCD2 is also associated with worse prognosis in patients with lymph node positive colorectal cancer, BRCA1/2 deficient breast tumors, ovarian carcinoma as well as metastatic melanoma." (PMID 32165999, 2020). "We have previously shown that FANCD2 expression is reduced in BRCA negative patients with a high genetic risk of developing ovarian cancer based on the patient’s personal and family history of cancer." (PMID 32165999, 2020). "We also observed that patients with FANCD2 span mutation were slightly younger than those without FANCD2 mutations, although not significantly, suggesting that FANCD2 span mutation may be associated with early onset of ovarian cancer." (PMID 38509102, 2024). "In addition to the known ovarian cancer high-risk genes, we found that germline mutations in FANCD2 and RECQL4 may be associated with hereditary and early onset of ovarian cancer." (PMID 38509102, 2024). "Other HRR pathway-related genes (ATM, ATR, CDK12, FANCA, FANCD2 and RAD50) were also found to play an essential role in ovarian cancer pathogenesis." (PMID 36729997, 2022). "To identify the cytoplasmic functions of FANCD2, we immunoprecipitated cytoplasmic FANCD2 binding proteins in OSE cells from an ovarian cancer patient." (PMID 32165999, 2020). "Fifteen of these 43 compounds were then confirmed to inhibit IR-induced FANCD2 foci formation in multiple cell lines, including PD20-FANCD2, U2OS, HeLa and TOV21G + FANCF ovarian cancer cells, using a wide range of drug concentrations (and data not shown)." (PMID 22537224, 2012).
ovarian carcinoma (continued). "One lead compound that interfered with cisplatin-induced FANCD2 monoubiquitylation and sensitized breast and ovarian cancer cells to cisplatin was the natural and relatively non-toxic compound curcumin." (PMID 18325101, 2008).
glioma (22 papers, 2014 to 2026). A benign or malignant brain and spinal cord tumor that arises from glial cells (astrocytes, oligodendrocytes, ependymal cells). "In glioma, cell death-related risk signatures (FANCD2, RRM2, BMP2, NFE2F2, MYD88) have been identified and validated using machine learning." (PMID 40559911, 2025). "Subsequently, ROC curve analysis suggested that the AUC values of WWTR1, STEAP3, SLC39A14, NOTCH2, IREB2, HIF1A, and FANCD2 were all 1.000, indicating their potential as diagnostic biomarkers for gliomas." (PMID 37978473, 2023). "FANCD2 was identified as a prognostic gene associated with poor prognosis in colon cancer, lung adenocarcinoma, clear cell renal cell carcinoma, and glioma." (PMID 36733386, 2022). "When exposed to cisplatin, all three cell types exhibited robust monoubiquitination of FANCI and FANCD2, demonstrating that FA pathway activation is a conserved response in glioma." (PMID 41486508, 2026). "Seven ferroptosis-related hub genes, namely SLC39A14, WWTR1, STEAP3, NOTCH2, IREB2, HIF1A, and FANCD2, were identified, all of which were highly expressed in glioma." (PMID 37978473, 2023). "FANCD2 expression was found to be correlated with glioma grade, and high expression was found to predict worse survival in lung adenocarcinoma." (PMID 37400829, 2023). "In conclusion, we identify seven ferroptosis-associated genes (SLC39A14, WWTR1, STEAP3, NOTCH2, IREB2, HIF1A, and FANCD2) in gliomas, all of which are highly expressed." (PMID 37978473, 2023). "In low-grade gliomas, FANCD2, the ferroptosis-related gene, holds value as prognostic indicator, which can be used as a diagnostic and prognostic biomarker." (PMID 37978473, 2023). "Recent studies have shown that Fanconi anemia group D2 protein (FANCD2) can modulate the effect of carboplatin therapy in children with high-grade gliomas." (PMID 35674307, 2022). "In glioma cell lines resistant to carboplatin, the sensitivity of FANCD2 to repair damaged DNA formation is enhanced." (PMID 35674307, 2022). "FANCD2 was correlated with glioma grade, and pharmacological inhibition of the pathway sensitized glioma cells to chemotherapeutic agents." (PMID 36566214, 2022). "Regarding major nodes in the DNA repair network, ERCC1, FANCD2, and RAD17 have been associated with therapy resistance in gliomas and other tumor types." (PMID 31969990, 2020). "Overall, these data are consistent with previous mRNA studies, and demonstrate that FANCD2 protein expression increases with glioma grade and is active and responsive to chemotherapeutic agents." (PMID 25071006, 2014). "Consistent with a previously reported defective FA pathway, the glioma cell line U138 displayed reduced endogenous levels of FANCD2 and an inability to activate the FA pathway following TMZ treatments." (PMID 25071006, 2014). "Previous studies have demonstrated that FANCD2 is overexpressed in high-grade gliomas and depletion of FANCD2 may serve as a potential strategy for the treatment high-grade gliomas." (PMID 34249910, 2021). "However, 46% and 93% of grade III and grade IV gliomas respectively stained positive for FANCD2 expression." (PMID 25071006, 2014). "In order to verify our hypothesis, we found that knockdown of lncRNA TMEM161B-AS1 inhibited the proliferation, migration, invasion of glioma cells, and promoted apoptosis and ferroptosis by down-regulating the expression of FANCD2 and CD44 through sponging hsa-miR-27a-3p." (PMID 34689169, 2021). "We found that the expression levels of FANCD2 and CD44 genes were related to the survival of Chinese glioma patients according to the data from the mRNAseq_325 dataset in the CGGA database." (PMID 34689169, 2021). "First of all, the specific molecular mechanisms of the effects of FANCD2 and CD44 on the proliferation, migration and invasion of glioma cells need to be elucidated." (PMID 34689169, 2021).
glioma (continued). "Additionally, the mRNA expression levels of MST4/STK26, USP14, and ALKBH5 were positively correlated with ALKBH5 target genes, including FANCD2, FANCI, MKI67, and RAD51 within the TCGA and CGGA glioma datasets." (PMID 39990235, 2025). "Neither mutations in the tumor suppressor gene PTEN, which is commonly altered in glioma, nor in FANCD2, which is essentially involved in DNA repair, have been described in ependymomas yet." (PMID 38265489, 2024). "Apart from that, elevated transmembrane protein 161B-AS1 facilitates the malignancies of glioma cells and TMZ tolerance, where it sponges hsa-miR-27a-3p to enhance the expression of ferroptosis-related genes like fanconi anemia complementation group D2 (FANCD2) and CD44141." (PMID 39309434, 2024). "Based on the results, we speculate that there may be a lncRNA-miRNA-gene network among lncRNA TMEM161B-AS1, hsa-miR-27a-3p, FANCD2 or CD44, which involves in the occurrence of gliomas." (PMID 34689169, 2021). "Previous findings have shown that downregulation of FANCD2 expression by siRNA-mediated approach in U87 and T98MG cells can increase cellular sensitivity to glioma chemotherapeutic agents, TMZ and BCNU, demonstrating that FA repair pathway is involved in glioma resistance to DNA alkylating agents." (PMID 25337721, 2014). "Given that normal brain tissue, or benign tumours derived from a non-glial lineage do not express FANCD2, we postulate that inhibition of the FA pathway in high-grade gliomas represents a novel therapeutic window to improve the treatment of these incurable tumours." (PMID 25071006, 2014). "However, previous studies of CAPG, FANCD2, HMOX1, HSPB1, RRM2, and STEAP3 did not develop any new clinical therapy in glioma." (PMID 36566214, 2022).
lung carcinoma (17 papers, 2008 to 2025). "FANCD2 expression facilitates tumor immune escape in lung cancer by suppressing the immune microenvironment, while patients with high expression of FANCD2 exhibited higher tumor mutation burden (TMB) indicating greater responses to immunotherapy." (PMID 36685883, 2022). "A risk model for predicting therapeutic responses obtained better predictive efficiency when combined with FANCD2 expression and tumor mutation burden in lung cancer." (PMID 36313179, 2022). "To evaluate and compare novel-targeted agents in the background of FA deficiency, we utilized RNAi technology to render several lung cancer cell lines FANCD2 deficient." (PMID 25566506, 2014). "Similar results have been shown for AITC which induced replication stress-associated DNA damage in human lung cancer cells, where FANCD2 repair protein formed foci at stalled or collapsed replication forks, ATM/ATR, Rad18, and Chk1 were activated, and γH2A.X level was elevated." (PMID 31123866, 2020). "Consistently, the co-knockdown of FANCD2 and POLQ in two lung cancer cell lines resulted in hypersensitivity to cisplatin, as compared with the single knockdown of FANCD2 or POLQ." (PMID 34206946, 2021). "Herein, we report our evaluation of FA deficiency in a series of tumors from patients with NSCLC and the response of lung cancer cells with reduced FANCD2 expression (FANCD2 knock-down cell) to treatment with inhibitors of PARP, CHK1, and BCL-2/XL." (PMID 25566506, 2014). "We, therefore, propose a model of the role of FANCD2 suppression in cigarette smoke-induced lung cancer in which cigarette smoke suppresses FANCD2 in vivo, creating recurring cycles of cytotoxicity and CIN." (PMID 18475298, 2008). "Another study found that ATM inhibition or loss of FANCD2 conferred a reduction in HRR and RAD51 foci formation in lung cancer, which is consistent with our finding that complete ATM loss in NGP cells impaired HRR through the downregulation of FANCD2 and RAD51 expression." (PMID 37020276, 2023). "Biologically, FANCD2 destabilization upon RPS27L knockdown caused decreased formation of FANCD2 foci as well as reduced formation of γH2AX foci, leading to sensitization of lung cancer cells to MMC." (PMID 33051438, 2020). "We used the FATSI method to evaluate FANCD2 foci formation or lack thereof in lung cancer samples." (PMID 25566506, 2014). "Biologically, RPS27L knockdown suppresses FANCD2 foci formation and impairs ICL repair upon exposure to ICL-inducing agent mitomycin C (MMC) in lung cancer cells." (PMID 33051438, 2020). "Here we reported that RPS27L also regulates ICL repair via stabilization of FANCD2 and FANCI in lung cancer cells." (PMID 33051438, 2020). "Analyses of ATM serine 1981 and Chk1 serine 345 phosphorylation, and FANCD2 monoubiquitination revealed that ATM and ATR kinase activation and FA pathway signaling are intact in the lung cancer cell lines examined." (PMID 26438152, 2015). "Surprisingly, it appears that FANCJ regulates FANCD2 stability through 2 separate pathways, as both MG-132 and Z-VAD-FMK restored FANCD2 levels to near normal levels in H1299 lung cancer cells (84% and 93% of normal, respectively)." (PMID 26336824, 2015). "In summary, we identified that the four ferroptosis suppressor genes, ACSL3, CISD1, FANCD2, and SLC3A2, could increase the cancer stemness, indicating that the lower the ferroptosis level in lung cancer cells, the higher the tumor heterogeneity." (PMID 34434214, 2021). "No defects in ATM, ATR or Chk1 kinase activation, or FANCD2 monoubiquitination were identified in the lung cancer cell lines examined, including Calu6, and major alterations in these pathways were not identified in the TCGA database." (PMID 26438152, 2015).